DHCR24 (24-dehydrocholesterol reductase)
Description:
Catalyzes the reduction of the delta-24 double bond of sterol intermediates during cholesterol biosynthesis. In addition to its cholesterol-synthesizing activity, can protect cells from oxidative stress by reducing caspase 3 activity during apoptosis induced by oxidative stress. Also protects against amyloid-beta peptide-induced apoptosis.
Synonyms: KIAA0018; seladin-1; DCE; Nbla03646; SELADIN1
Tractability: Small molecule: an approved drug acts on it; a high-quality ligand is known. Antibody: UniProt predicts a signal peptide or a membrane-spanning region. PROTAC: ubiquitination databases record sites on it; its protein half-life has been measured; a small molecule that binds it is known.
Target class: Enzyme; Oxidoreductase
Gene: Protein-coding gene on chromosome 1 (54,849,627 to 54,887,207, reverse strand). Ensembl gene ENSG00000116133.
Subcellular location: Endoplasmic reticulum membrane; Golgi apparatus membrane
Pathways (Reactome):
Metabolism: Cholesterol biosynthesis from zymosterol (modified Kandutsch-Russell pathway); Cholesterol biosynthesis via desmosterol (Bloch pathway); Zymostenol biosynthesis via lathosterol (Kandutsch-Russell pathway)
Gene Ontology:
Molecular function: Delta24(24-1) sterol reductase activity; Delta24-sterol reductase activity; enzyme binding; oxidoreductase activity, acting on the CH-CH group of donors, NAD or NADP as acceptor; peptide antigen binding; protein binding; FAD binding; flavin adenine dinucleotide binding
Biological process: cholesterol biosynthetic process; tissue development; skin development; negative regulation of cell population proliferation; Ras protein signal transduction; response to hormone; steroid metabolic process
Cellular component: endoplasmic reticulum; endoplasmic reticulum membrane; Golgi membrane; membrane; nucleus
Genetic constraint (gnomAD): Loss-of-function variants: 28 observed, 64.26 expected, observed/expected ratio (o/e) 0.44, 90% interval 0.32 to 0.6. The upper end of that interval is the gene's LOEUF score, 0.6, which puts it in group 2 of 6, group 1 being the genes least tolerant of losing a copy. Missense variants: 538 observed, 712.83 expected, observed/expected ratio (o/e) 0.75, 90% interval 0.7 to 0.81. Synonymous variants: 261 observed, 290.67 expected, observed/expected ratio (o/e) 0.9, 90% interval 0.81 to 1.
Gene-disease validity (ClinGen):
ClinGen rates the evidence that DHCR24 causes each of these diseases.
desmosterolosis (autosomal recessive): Definitive. Desmosterolosis is a very rare sterol biosynthesis disorder characterized by multiple congenital anomalies, failure to thrive, and intellectual disability, with elevated levels of desmosterol.
Homologues: Orthologues: chimpanzee DHCR24 (99% identical), macaque DHCR24 (99% identical), rat Dhcr24 (97% identical), dog DHCR24 (97% identical), mouse Dhcr24 (97% identical), guinea pig DHCR24 (96% identical), rabbit DHCR24 (96% identical), pig DHCR24 (87% identical), zebrafish dhcr24 (79% identical), tropical clawed frog dhcr24 (78% identical), Caenorhabditis elegans dhcr-24 (49% identical).
Diseases named in the same sentence as DHCR24 in open-access papers:
DHCR24 is named in the same sentence as 100 diseases in open-access papers, as found by Europe PMC text mining. Sharing a sentence is not in itself a finding about the gene and the disease. The quoted sentences say what the papers report.
Alzheimer disease (28 papers, 2006 to 2025). A progressive, neurodegenerative disease characterized by loss of function and death of nerve cells in several areas of the brain leading to loss of cognitive function such as memory and language. "DHCR24 encodes seladin−1, which protects against amyloid-beta peptide-induced toxicity, and is downregulated in affected neurons of patients with Alzheimer’s disease." (PMID 24170811, 2014). "The Dhcr24 gene is one of the major target genes that is associated with Alzheimer’s disease and type 2 diabetes through regulating cholesterol levels in the brain, and it is also associated with lipid metabolism as a new causal biomarker of type 2 diabetes risk." (PMID 40941077, 2025). "Moreover, DHCR24 has been linked to Alzheimer’s disease (AD), oncogenic and oxidative stress, hepatitis C virus (HCV) infections, differentiation of T helper-17 cells, development of foam cells, and prostate cancer." (PMID 36985615, 2023). "DHCR24 is also known as SELective Alzheimer’s Disease INdicator-1 (seladin-1) as it was shown to be downregulated in Alzheimer’s disease (AD)." (PMID 38672427, 2024). "DHCR24 is also named ‘selective Alzheimer’s disease indicator-1′ or Seladin-1 because of its connection with AD." (PMID 36674444, 2023). "DHCR24 is also named Selective Alzheimer disease indicator 1 (seladin-1) because it was first identified using neuronal cells from Alzheimer’s disease (AD) patients." (PMID 36674444, 2023). "A growing body of evidence indicates that DHCR24 is downregulated in the brain of various models of Alzheimer’s disease (AD), such as astrocytes isolated from AD mice." (PMID 35804281, 2022). "24-Dehydrocholesterol Reductase (DHCR24), also known as Seladin-1 (selective Alzheimer’s disease indicator-1), has decreased expression in Alzheimer’s susceptible brain regions." (PMID 34949154, 2022). "It has been reported that the activity of the gene coding for the enzyme DHCR24 was selectively reduced in the affected areas of the brain in Alzheimer’s disease." (PMID 32041309, 2020). "DHCR24, as an enzyme that metabolizes desmosol to cholesterol, was closely related to aging diseases such as Alzheimer’s disease." (PMID 32041309, 2020). "DHCR24 (3-β-hydroxysteroid-Δ-24-reductase), also known as seladin-1 (selective Alzheimer’s disease indicator-1), was initially identified as being expressed at lower levels in the affected as compared to unaffected brain regions in AD patients." (PMID 29115990, 2017). "Reduced expression of DHCR24 was observed in Alzheimer’s disease." (PMID 37138705, 2023). "Nevertheless, the potential role of DHCR24 in Alzheimer disease and other neurodegenerative diseases is still unknown." (PMID 33967735, 2021). "Previous studies found that there is a significant reduction in the expression of new gene in specific vulnerable brain regions in Alzheimer's disease (AD) patients, which was named selective AD indicator 1 (Seladin-1), or 3β-hydroxysterol-Δ24 reductase (DHCR24)." (PMID 33967735, 2021). "Moreover, studies indicate that DHCR24 transcription is selectively down-regulated in brain regions vulnerable to Alzheimer's disease in the transgenic mouse model of AD." (PMID 33967735, 2021). "Hypomethylation of CHD5 (−11.76%), which regulates genes implicated in aging and Alzheimer’s disease, and hypermethylation of DHCR24 (10.39%), which has neuroprotective characteristics and is downregulated in neurons of Alzheimer’s disease patients was observed in the reduced cognition group." (PMID 32033187, 2020). "In addition, differential methylation of two genes associated with Alzheimer’s disease (CHD5 and DHCR24) was also observed in this study." (PMID 32033187, 2020). "DHCR24, involved in the de novo synthesis of cholesterol and protection of neuronal cells against different stress conditions, has been shown to be selectively downregulated in neurons of the affected brain areas in Alzheimer’s disease." (PMID 29115990, 2017).
Alzheimer disease (continued). "DHCR24 was originally known as Seladin-1 gene (Selective Alzheimer’s Disease Indicator-1) as its expression was initially discovered to be down-regulated in regions of the brain vulnerable to Alzheimer’s disease (AD)." (PMID 26557426, 2015). "For example, DHCR24 and PIN1 are associated with Alzheimer’s disease." (PMID 24170811, 2014). "Thus, epigenetic modification could regulate DHCR24 gene expression which contributes to Late-Onset Alzheimer's Disease." (PMID 35296367, 2022). "In addition to PCSK9, expression data highlights the roles of DHCR24 and USP24 in SMI and CMD: DCHR24 has been shown to have a neuroprotective role during inflammation with loss-of DCHR24 expression being observed in Alzheimer’s disease." (PMID 35501368, 2022). "For example, the mechanisms were studied whereby desmosterol [3-β-hydroxysterol delta-24-reductase (DHCR24)], also named SELective Alzheimer’s Disease INdicator-1 (seladin-1), may be involved in the potential role of SERMs in their effects in Alzheimer’s disease." (PMID 33066585, 2020). "24-Dehydrocholesterol reductase (DHCR24) is a key regulatory factor involved in cholesterol synthesis and homeostasis and is downregulated in the brain of Alzheimer’s disease (AD) models." (PMID 39796168, 2025). "Cumulating Evidences suggest that epigenetic factors that are involved in Late-Onset Alzheimer's Disease (LOAD), such as methylation and acetylation, also obviously regulate DHCR24 expression and activity." (PMID 35296367, 2022). "In addition, in the common carp liver, the KEGG pathway analysis showed that Alzheimer’s disease was related to genes INSR, GAPDHS, BAX, DHCR24, PPARG, ENO1, and VEGFA." (PMID 35741857, 2022). "In AD patients, it has been reported that DHCR24 transcription and protein expression were selectively down-regulated in the brain areas affected in Alzheimer's disease, but the reasons for this decrease are not known." (PMID 35296367, 2022).
desmosterolosis (15 papers, 2014 to 2024). "DHCR24 deficiency is the underlying mechanism for desmosterolosis (OMIM 602398), a genetic syndrome characterized by elevated desmosterol concentrations and multiple congenital anomalies." (PMID 38672427, 2024). "The defect in DHCR24 is associated with a rare autosomal recessive developmental disorder called desmosterolosis characterized by desmosterol accumulation." (PMID 37138705, 2023). "Such an alteration was also evident in a subset of known DHCR24 variants associated with desmosterolosis, allowing us to identify at the molecular level the residue interaction network essential for the proper functioning of the protein and its cofactor." (PMID 38239854, 2023). "In conclusion, this report presents a novel DHCR24 missense variant, p.M169T, shows its molecular mechanisms, and links them to the desmosterolosis presentation." (PMID 38239854, 2023). "Mutation in the DHCR24 gene in humans causes a decrease in the DHCR24 enzyme activity, leading to desmosterolosis (MIM 602398), which is a rare and severely autosomal recessive genetic disease." (PMID 36985615, 2023). "DHCR24 variants have been associated with desmosterolosis, resulting in the production of altered 24-dehydrocholesterol reductase and consequent decreased cholesterol production." (PMID 38239854, 2023). "Desmosterolosis is caused by mutations in DHCR24, lead to the elevated desmosterol levels and decreased level of cholesterol in the patient's brain, resulting in multiple congenital anomalies including white matter atrophy and synaptic abnormality." (PMID 35296367, 2022). "This gene encodes the enzyme 24-dehydrocholesterol reductase that converts desmosterol to cholesterol and different mutations in this gene has been shown to cause desmosterolosis (OMIM:602398; Refs.32,33)." (PMID 33116219, 2020). "Desmosterolosis is an autosomal recessive disorder of cholesterol biosynthesis caused by biallelic mutations of DHCR24 (homozygous or compound heterozygous), which encodes 3-β-hydroxysterol Δ-24-reductase." (PMID 24961299, 2014). "In addition, mutations in DHCR24 enzyme, which converts desmosterol into cholesterol, leads to desmosterolosis, an autosomal recessive developmental disorder." (PMID 35296367, 2022). "Mutations in the DHCR24 gene may cause desmosterolosis, an autosomal recessive disease characterized by high levels of desmosterol." (PMID 28194238, 2017). "Dhcr24 knockout mice died within hours of birth from a series of skin developmental defects related to desmosterol accumulation in the epidermis, and mutations in the DHCR24 gene lead to desmosterolosis, an autosomal recessive disease characterized by developmental and growth retardation." (PMID 38775844, 2024). "Congenital malformations and developmental abnormalities caused by desmosterolosis are attributed to the fetus being unable to effectively obtain sufficient exogenous cholesterol from the mother, and endogenous cholesterol is difficult to synthesize because of the abnormally low activity of DHCR24." (PMID 36985615, 2023). "Of note, the excess of desmosterol is detrimental, as proven in individuals affected by desmosterolosis, a developmental disorder due to the defective DHCR24 gene." (PMID 38671883, 2024). "Homozygous or compound heterozygous defects in two terminal enzymes participating in cholesterol synthesis, DHCR7 or DHCR24, cause the dysmorphological conditions Smith-Lemli-Opitz syndrome (OMIM #270400) and desmosterolosis (OMIM #602398), respectively." (PMID 33524375, 2021). "A third autosomal recessive disease with direct links to cholesterol is desmosterolosis (OMIM 602398), which is caused by mutations in the 24-dehydrocholesterol reductase (DHCR24)." (PMID 31284522, 2019). "Regretfully, because desmosterolosis by DHCR24 mutation is a lethal disorder, the mice model lacking one or both alleles of DHCR24 gene is still lack." (PMID 35296367, 2022).
desmosterolosis (continued). "Examples of such congenital disorders and the affected enzymes include Smith-Lemli-Opitz syndrome (SLOS; DHCR7, OMIM# 270400), desmosterolosis (DHCR24, OMIM# 602398), lathosterolosis (sterol-C5-desaturase, OMIM# 607330), and mevalonate kinase (MVK, OMIM# 251170) deficiency." (PMID 33662384, 2021). "Furthermore, in a mouse model of desmosterolosis, DHCR24-KO mice brains showed complex changes in expression of lipid and sterol transcripts and synaptic plasticity transcripts, and the decrease of membrane cholesterol and disruption of membrane lipid raft and increased arborization synapse." (PMID 35296367, 2022).
prostate carcinoma (11 papers, 2014 to 2024). A carcinoma that arises from epithelial cells of the prostate gland. "For example, androgen-responsive elements can upregulate the enzyme 3β-hydroxysterol Δ24-reductase (DHCR24) in AR-positive prostate cancer cells, thereby promoting cholesterol accumulation." (PMID 37312170, 2023). "DHCR24 is also overexpressed in bladder cancer, melanoma and endometrial cancer, prostate cancer, and breast cancer." (PMID 36518627, 2022). "Enrichment analysis of validated miRNA–gene interactions followed by targeted pathway analysis showed that both mir-629-5p and miR-194-5p target the DHCR24 gene, a central regulator of steroid biosynthesis, which is frequently altered in prostate cancer cells." (PMID 34828332, 2021). "DHCR24, also known as seladin-1, is regarded as androgen induced genes due to its consistent over-expression in prostate cancer than normal prostate tissue." (PMID 31295943, 2019). "These included FDFT1, which is expressed at higher levels in human prostate cancer specimens and in aggressive cancers, and DHCR24, also known as seladin-1, an androgen regulated gene that is expressed significantly higher in prostate cancer and is positively related to T stage." (PMID 29156692, 2017). "The progression from low-grade to high-grade prostate carcinoma and metastases is mediated by down-regulation of the androgen receptor target genes, including DHCR24 (24-Dehydrocholesterol Reductase)." (PMID 27206673, 2016).
melanoma (10 papers, 2021 to 2024). A malignant, usually aggressive tumor composed of atypical, neoplastic melanocytes. "The mRNAsi results showed that elevated intracellular cholesterol was positively associated with melanoma stemness, through activation of DHCR24 in cholesterol biosynthesis or inhibition of efflux by ABCA1, and ABCG1." (PMID 38775844, 2024). "The results showed that the expression of DHCR24 was significantly higher in malignant melanoma, especially in metastatic melanoma, compared with control." (PMID 38775844, 2024). "FASN and DHCR24 lipogenic enzymes were shown to be involved in the modulation of BRAFi response in melanoma." (PMID 38338838, 2024). "Next, we validated that cholesterol rescued vemurafenib-induced proliferation blockade and apoptosis as DHCR24 forced expression, highlighting the importance of cholesterol in melanoma therapy." (PMID 38775844, 2024). "The treatment of orlistat targeting FASN in melanoma LM16R cells leads to the upregulation of DHCR24, activating compensatory pathways that support drug-resistant growth." (PMID 38921444, 2024). "We also found that DHCR24 strongly upregulated the expression of CYP27A1 in melanoma cells, indicating a positive feedback loop leading to cellular accumulation of 27HC." (PMID 38775844, 2024). "We observed that forced expression of DHCR24 promoted tumor growth in mouse xenografts, whereas knockdown of DHCR24 blocked cells in S phase and resulted in significant inhibition of invasion and migration in melanoma cells." (PMID 38775844, 2024). "DHCR24 is expressed at higher levels in melanoma metastases compared to primary tumors, and its elevated expression is associated with resistance to apoptosis." (PMID 38921444, 2024). "Suppressing DHCR24 with the inhibitor U18666A enhanced the sensitivity of the melanoma cells to hydrogen peroxide, demonstrating the protective role of DHCR24 against oxidative stress." (PMID 38921444, 2024). "As the levels of the lipogenic enzymes FASN and DHCR24 differed in melanoma patients with respect to controls, we proceeded further to lipidomic profiling studies." (PMID 38338838, 2024). "In the present study, based on IHC results from clinical tissue microarray, DHCR24 was found to be highly expressed in melanoma patients, and knocking down DHCR24 blocked the cells in S phase and inhibited the proliferation and migration of melanoma cells." (PMID 38775844, 2024). "We quantitatively assessed the levels of FASN and DHCR24 enzymes in melanoma patients and healthy control subjects in relation to plasma TG and CHOL and tested plasma lipid composition by untargeted/targeted lipidomic approaches." (PMID 38338838, 2024). "The relevance of SCD1, MVK, FASN and DHCR24 in melanoma progression or drug resistance is already supported by our previous studies and by the literature." (PMID 35912092, 2022). "These pre-clinical and clinical findings urge further investigation of statins or the novel selective DHCR24 inhibitors in melanoma patients." (PMID 35626014, 2022). "DHCR24 is required for cellular response to oncogenic and oxidative stress, is up-regulated in melanoma metastases compared to the corresponding primary tumor, and is associated with resistance to apoptosis." (PMID 34068792, 2021). "Accordingly, forced expression of CYP27A1 only in melanoma cells increased cellular 27HC content, caused vemurafenib resistance, and promoted melanoma spheroid propagation in both A375 and A2058 melanoma cells, independent of DHCR24 induction." (PMID 38775844, 2024). "Indeed, our data showed that forced expression of DHCR24 increases cellular 27HC content without statistically affecting cholesterol content in melanoma cells and, moreover, is associated with melanoma spheroid expansion and vemurafenib resistance." (PMID 38775844, 2024).